TTR (transthyretin)
Diseases named in the same sentence as TTR in open-access papers (continued):
Sharing a sentence is not in itself a finding about the gene and the disease.
chronic kidney disease (11 papers, 2010 to 2025). Impairment of the renal function secondary to chronic kidney damage persisting for three or more months. "The 7 other positive tests included amyloidosis (TTR, N = 3), Alport syndrome (COL4A3, N = 2), polycystic kidney disease (PKD1, N = 1), and susceptibility to end stage renal disease (APOL1, N = 1)." (PMID 40126616, 2025). "TTR was reported as a better and suitable marker for nutrition assessment in patients with chronic renal failure." (PMID 26608305, 2015). "The kidneys play an important role in the metabolism of vitamin A and its transport proteins and it is well documented that a reduced kidney function due to acute or chronic renal failure is associated with increased serum concentrations of ROH, RBP4 and TTR." (PMID 22151790, 2011). "Transthyretin is an early marker of under-nutrition; its plasma level is decreased in case of liver failure, inflammatory syndrome and increased in case of chronic renal insufficiency." (PMID 21044301, 2010).
multiple myeloma (11 papers, 2015 to 2025). "In addition to 18F-florbetapir, the use of 18F-florbetaben PET/CT for monitoring anti-inflammatory (AA), anti-myeloma (AL) and TTR-stabilizing (TTR) therapy were also evaluated." (PMID 36290299, 2022).
neuroblastoma (11 papers, 2011 to 2025). Neuroblastoma (NB) is the most common solid, extracranial childhood tumor. "Studies performed in human embryonic kidney and neuroblastoma cells expressing mutated TTR demonstrated that also in FAP there is a weakened autophagic response that can be modulated by curcumin and TUDCA." (PMID 28583160, 2017). "A previous study showed that binding of HDAC1 to the NEP promoter and TTR promoter was decreased in neuroblastoma cells expressing the APP695 isoform." (PMID 32950104, 2021). "SH-SY5Y neuroblastoma cells, used as a neuronal function and differentiation model, were incubated with TTR pre-incubated with Aβ1–42, TTR alone, or Aβ alone." (PMID 33256250, 2020). "LUT showed to be able to suppress TTR-induced toxicity in neuroblastoma cells in a cell-based viability assay with a comparable effect as diflunisal and to mediate its stabilising effect on TTR in vivo in an established D. melanogaster model of FAP." (PMID 32419519, 2020). "We show here that luteolin efficiently prevents the cytotoxic effects of TTR on a human neuroblastoma cell line and rescues the pathological phenotype in a Drosophila melanogaster model of FAP." (PMID 26020516, 2015). "The cytotoxicity of recombinant human TTR (TTR) in SH-SY5Y neuroblastoma cells has previously been demonstrated, and this was the experimental system used throughout the present investigation." (PMID 26020516, 2015). "In the human neuroblastoma cell line SK-N-BE, TTR inhibited ultrastructural changes characteristic of apoptosis." (PMID 22112803, 2011). "Pre-incubation of Aβ with TTR also suppressed caspase-3 activation in the undifferentiated human neuroblastoma SH-SY5Y cell line and the cytotoxicity induced by Aβ oligomers on SH-SY5Y cells differentiated by retinoic acid treatment." (PMID 22112803, 2011). "A neuroblastoma cell line overexpressing the APP intracellular domain (AICD), evidenced that TTR is epigenetically regulated by this fragment in the brain." (PMID 32197355, 2020). "Another study described that the expression of TTR in the hippocampus, in primary murine hippocampal neurons, and a SH-SY5Y neuroblastoma cell line is significantly enhanced by the heat shock factor 1 (HSF1)." (PMID 32197355, 2020). "To evaluate the ability of TBBPA to suppress TTR-induced toxicity, we used a cell-viability assay based on human SH-SY5Y neuroblastoma cells." (PMID 27093678, 2016). "We used the human neuroblastoma cell line IMR-32, which has been established as a model for studies of TTR toxicity, and WST-1 assay to measure cytotoxic effects." (PMID 23390551, 2013).
spinal muscular atrophy (11 papers, 2018 to 2025). A motor neuron disease that affect the muscles, and characterized by muscle weakness and atrophy resulting from progressive degeneration and irreversible loss of the anterior horn cells in the spinal cord (i.e., lower motor neurons) and the brain stem nuclei. "We selected spinal muscular atrophy (SMA), Duchenne muscular dystrophy (DMD), Pompe disease, Limb-girdle muscular dystrophies (LGMDs) and Transthyretin-related peripheral neuropathy." (PMID 32946487, 2020).
Thrombocytopenia (11 papers, 2019 to 2026). A reduction in the number of circulating thrombocytes. "Disease-modifying treatments, like the transthyretin stabilizer tafamidis, can lead to blood cell line derangements, for example, thrombocytopenia, as seen in this case." (PMID 41384196, 2025). "IV: Intravenous; N: Number of participants; CT: Clinical trial; TTR: Transthyretin; SC: Subcutaneously; RBP4: Retinol-binding protein 4; QoL: Quality of life; QoL-DN: Quality of life-diabetic neuropathy; MAE: Major adverse event; GN: Glomerulonephritis; TCP: Thrombocytopenia." (PMID 39044869, 2024).
breast cancer (10 papers, 2007 to 2024). A primary or metastatic malignant neoplasm involving the breast. "Accumulation of amyloid in breast cancer is a well‐known phenomenon, but only immunoglobulin light‐chain amyloidosis (AL) or transthyretin (TTR) amyloid had been detected in human breast tumor samples previously." (PMID 34592066, 2022). "Among this five-peak panel, three (C3a-desArg, TTR and ApoH) were increased in sera of the breast cancer patients compared to that of HV subjects, while ApoCI and ApoAI were decreased in cancer." (PMID 24935269, 2014). "In our study, we identified the peak at m/z 13870 as full-length TTR; however, a peak at m/z 13756 detected by Q10 protein chip was also significantly upregulated in the serum of breast cancer patients." (PMID 24935269, 2014). "Leptomeningeal metastasis of breast cancer patients showed decreased levels of TTR, and a 2D electrophoresis study also showed decreased levels of TTR in cerebrospinal fluid of Guillain-Barré syndrome patients." (PMID 18682810, 2008).
ischemic stroke (10 papers, 2011 to 2025). A stroke disorder caused by obstruction of blood flow to the brain, due to thrombotic (local blood clot formation) or embolic (due to a blood clot or other material traveling from another site) event. "As TTR is involved in thyroid hormone transport we intended to explore the possible association between levels of this protein and outcome in ischemic stroke." (PMID 28636639, 2017). "Notably, reduced TTR is associated with poor prognosis in ischemic stroke patients." (PMID 31242583, 2019). "Among these target proteins, Fyn and TTR are the overlapping nodes of ischemic stroke-related proteins, which have important value for future research." (PMID 36133785, 2022). "In a clinical trial, 117 ischemic stroke patients were examined, and the results showed that the patients who had lower serum levels of TTR, had a lower GOSE outcome." (PMID 33224232, 2020). "In another study, 81 ischemic stroke patients were examined, and the results showed the baseline serum level of TTR was an important predicting factor for the one-year mortality and clinical outcome." (PMID 33224232, 2020). "Patients suffering from an ischaemic stroke with an unfavourable outcome were found to have significantly lower TTR serum levels on admission." (PMID 31637049, 2019). "Reduced AFM and TTR, which we found in the cardioembolic vs. large-vessel stroke comparison and in the CBS deficiency, were also observed in Han Chinese ischemic stroke patients." (PMID 31242583, 2019). "The current study was designed to assess the prognostic value of serum TTR for functional outcome (at the time of hospital discharge) and long-term (one-year) overall mortality in ischemic stroke patients." (PMID 28636639, 2017). "In young patients with ischemic stroke, serum prealbumin (transthyretin, PA) was also an independent predictor of clinical outcome." (PMID 22254136, 2011). "The higher rate of ischemic stroke may be related to a suboptimal TTR control in our population compared to other studies." (PMID 31023235, 2019).
liver disease (10 papers, 2005 to 2023). "For instance, an increase in the intensity of transthyretin protein spot of greater than 10% after bile fluid sample treatment with acetone and then 2D Clean-Up kit may indicate that transthyretin is a potential biomarker associated with that specific liver disease." (PMID 26966686, 2016). "Considering the fact that the liver is the source of serum TTR, it is reasonable to assume that the synthesis of this protein varies in the liver disease, such as cancer and hepatitis." (PMID 24497876, 2014). "Considering the fact that the liver is the source of serum TTR, it is reasonable to assume that the synthesis of this protein varies in liver diseases such as cancer and hepatitis." (PMID 24066001, 2013). "While we have focused in this review on the benefits of ASO/siRNA for treatment of TTR-related disease, the scope of therapeutic oligonucleotides might however go beyond liver disease." (PMID 26437390, 2015). "Additionally, we confirmed that RBP4, TTR and ROH levels in various liver diseases were markedly depressed, particularly in patients with c2-cirrhosis or hepato-cellular carcinoma, which is in accordance with results of previously published studies." (PMID 18752671, 2008).
monoclonal gammopathy (10 papers, 2010 to 2026). A condition characterized by the abnormal presence of monoclonal immunoglobulins in the blood or urine. "When a patient has evidence of both monoclonal gammopathy and a TTR mutation, it is even more challenging to identify which is the driving cause of symptoms." (PMID 39736876, 2024). "In patients with evidence of both monoclonal gammopathy and a TTR mutation, correct subtyping is even more challenging." (PMID 39736876, 2024). "Furthermore, in contrast to hATTR and AL, there is an absence of supportive biomarkers in wild-type ATTR, including a TTR gene mutation or monoclonal gammopathy, respectively." (PMID 34106429, 2021). "Only one false positive biopsy was found in a previously healthy 44-year-old male patient with a painful peripheral neuropathy without signs of monoclonal gammopathy and no TTR mutation." (PMID 33032630, 2020). "Additionally, this patient was confirmed to have no TTR gene mutations but to have a monoclonal gammopathy and a Perugini score of 2 and Dorbala score of 3 in PYP scintigraphy." (PMID 37460984, 2023).
Arrhythmia (9 papers, 2013 to 2025). Any cardiac rhythm other than the normal sinus rhythm. "Infiltrating misfolded transthyretin stiffens and disrupts cardiac structure, thereby compromising cardiac diastolic function and inducing cardiac arrhythmia." (PMID 40021267, 2025). "Although the clinical course of TTR-CA is dominated by HF and its manifestations, arrhythmias and conduction system diseases are also very common." (PMID 37025682, 2023). "Additional symptoms of TTR-FAP include hoarseness, coldness, decreased skin temperature, dyscoria, dysesthesia, muscle weakness and atrophy, dissociated anesthesia, and constitutional conditions such as weight loss, arrhythmia, edema, and burning." (PMID 23425518, 2013).
Cirrhosis (9 papers, 2008 to 2024). A chronic disorder of the liver in which liver tissue becomes scarred and is partially replaced by regenerative nodules and fibrotic tissue resulting in loss of liver function. "As expected, patients with cirrhosis had significantly lower serum concentrations of albumin, transferrin, transthyretin, pseudocholinesterase, and apolipoprotein AI compared to healthy individuals." (PMID 36652164, 2023). "The results we obtained indicated that serum AFP, tumor size, cirrhosis, tumor number and SNRNP70 NOD were valuable prognostic indicators for OS and TTR." (PMID 38500533, 2024). "We found proteins involved in hormone and vitamin transportation to be altered in patients with cirrhosis, for example, retinol‐binding protein (RBP4) and transthyretin (TTR)." (PMID 30824564, 2019). "Centrality and cluster screening identified hub genes, including APOE, TTR, CLU, and APOA1 in cirrhosis." (PMID 28224023, 2016). "HP α and α-2 isoforms, CLU, retinol binding protein, TTR, albumin, AGP and hemoglobin delta were decreased in the cirrhosis stage but IgJ chain was increased." (PMID 24066001, 2013). "In addition, the CKG highlighted the TTR-RBP complex (TTR and RBP4) as downregulated in patients with cirrhosis compared to healthy individuals." (PMID 35102292, 2022). "Consistent with the qPCR data, Western blotting indicated no significant changes in albumin or TTR expression (both P values > 0.05) in the liver tissue of rats with cirrhosis, whereas albumin and TTR levels were increased in rats treated with DPSCs (both P values < 0.05)." (PMID 29150644, 2017). "In addition, transferrin, BCHE, and apolipoprotein AI but not albumin and transthyretin display a stage-dependent decrease of serum concentrations from stable (SDC) and unstable decompensated cirrhosis (UDC) to pre-ACLF and ACLF as indicated by a significant Jonckheere-Terpstra test." (PMID 36652164, 2023).
Danon disease (9 papers, 2018 to 2026). A lysosomal glycogen storage disease characterized by severe cardiomyopathy and variable degrees of muscle weakness, frequently associated with intellectual deficit. "Nonetheless, the identification of a pathogenic mutation may help the cardiologist make tailored therapeutic choices and distinguish rare mimics such as Fabry disease, Danon disease, amyloidosis caused by TTR mutation, or atypical glycogenosis due to mutations in the PRKAG2 gene." (PMID 37048573, 2023). "Less frequent genetic causes are linked to infiltrative or metabolic diseases, such as GLA mutations in Fabry disease, TTR in transthyretin amyloidosis, LAMP2 in Danon disease, and PRKAG2 in glycogen storage cardiomyopathy." (PMID 40868441, 2025). "A small number of hypertrophic patients exhibit Fabry syndrome (GLA gene), Danon disease (LAMP2 gene), cardiac amyloidosis (TTR gene), Wolff—Parkinson—White syndrome (PRKAG2 gene), and mitochondrial cardiomyopathies." (PMID 37048573, 2023).
diabetic retinopathy (9 papers, 2019 to 2025). "This reduction in TTR could be associated with the prevalence of developing diabetic retinopathy (DR), and it has been proposed as a potential marker for the diagnosis and treatment of DR, justifying its crucial role in the development of neurological alterations." (PMID 39901093, 2025). "Transthyretin levels are decreased in the AH of diabetic retinopathy patients compared to controls and have been reported to suppress neovascularization." (PMID 41402737, 2025). "The fourth hypothesis posits that transthyretin (TTR), which is abundant in the vitreous of diabetic patients with myopia and is synthesized and secreted by retinal pigment epithelial cells, is substantially associated with the risk and severity of diabetic retinopathy (DR)." (PMID 38895184, 2024). "In ophthalmic diseases, abnormal TTR expression was reported in high myopia and diabetic retinopathy patients." (PMID 31615521, 2019). "TTR can inhibit retinal vascular proliferation in Diabetic Retinopathy." (PMID 38388341, 2024). "Transcriptome analysis of human retinal endothelial cells (hRECs) in diabetic retinopathy (DR) revealed the regulatory network of protective functions of TTR, implying that TTR co-ordinates oxidative stress, inflammation signaling, autophagy, and apoptosis in DR." (PMID 34359938, 2021). "In a different study, Shao and colleagues found several key genes involved in angiogenesis modulated by TTR in human retinal microvascular endothelial cells (hRECs) cultured with TTR in natural and simulated diabetic retinopathy (DR) environments (hyperglycemia and hypoxia)." (PMID 32197355, 2020). "The aim of the study was to demonstrate how transthyretin (TTR) could affect long non-coding RNA (lncRNA) of maternally expressed gene 3 (MEG3) and play important roles in diabetic retinopathy (DR)." (PMID 31847264, 2019).
hypothyroidism (9 papers, 2014 to 2025). Abnormally low levels of thyroid hormone. "These included hormones to treat TTR-HO-related neuroendocrine disorders: secondary or tertiary forms of adrenal deficiency, hypothyroidism, hypogonadism, growth hormone deficiency, and hypopituitarism as a combination of all." (PMID 39814823, 2025). "In adult TTR null mice, thyroid hormones (THs) failed to be transported from blood into cerebrospinal fluid inducing hypothyroidism condition, and this condition caused low level of apoptosis and normal fate of neural progenitor cells, suggesting that TTR regulates aNSCs indirectly." (PMID 30460064, 2017). "We were able to demonstrate that particularly patients with untreated (incident) hypothyroidism revealed substantial changes in the PTM pattern of TTR in comparison to healthy, euthyroid patients." (PMID 25311081, 2015). "Displacement of thyroid hormones from TTR by hydroxyl metabolites of PCB 180 further contributes to hypothyroidism." (PMID 25137063, 2014). "Across all types of hospitalizations, the most common secondary diagnoses were TTR-HO-related, including AVP-D (35%), hypopituitarism (21%), hypokalemia (18%), and hypothyroidism (12%)." (PMID 39814823, 2025). "The hydroxyl metabolite of PCB-180 replaces the thyroid hormone in transthyretin (TTR), which further leads to hypothyroidism." (PMID 36203481, 2022). "The average TTR serum concentration was 3.85 ± 2.95 μmol/l and was neither affected by hyperthyroidism nor by hypothyroidism." (PMID 25311081, 2015). "While the expression of TTR was not impacted by MMI‐induced fetal hypothyroidism, there was a significant downregulation in the expression of SERPINA7 in the MMI fetuses at GDs 66 and 76 relative to the equivalent age‐matched CONs (p = 0.011 and p < 0.001, respectively)." (PMID 40939099, 2025).
myocardial infarction (9 papers, 2014 to 2025). Gross necrosis of the myocardium, as a result of interruption of the blood supply to the area, as in coronary thrombosis. "Nevertheless, there are some situations that can lead to negative cardiac uptake: very early disease, rib fracture, recent myocardial infarction, premature or delayed acquisition and some TTR variants with usually neurological involvement." (PMID 38399526, 2024). "One case showed old myocardial infarction with advanced coronary artery disease and another one case had transthyretin-positive mild senile amyloidosis." (PMID 30959811, 2019). "Furthermore, in humans, TTR levels are significantly lower in patients with acute myocardial infarction, suggesting increase in TTR levels may have a cardioprotective effect in RIPC." (PMID 24454915, 2014).